TAX1BP3 (Tax1 binding protein 3)
Description:
May regulate a number of protein-protein interactions by competing for PDZ domain binding sites. Binds CTNNB1 and may thereby act as an inhibitor of the Wnt signaling pathway. Competes with LIN7A for KCNJ4 binding, and thereby promotes KCNJ4 internalization. May play a role in the Rho signaling pathway. May play a role in activation of CDC42 by the viral protein HPV16 E6.
Synonyms: TIP-1; TIP1
Tractability: Small molecule: a structure with a bound ligand is known. Antibody: UniProt places it where antibodies can reach, with medium confidence; its Gene Ontology location is reachable by antibodies, with medium confidence. PROTAC: ubiquitination databases record sites on it; its protein half-life has been measured.
Gene: Protein-coding gene on chromosome 17 (3,662,895 to 3,668,679, reverse strand). Ensembl gene ENSG00000213977.
Subcellular location: Cytoplasm; Nucleus; Cell membrane
Subcellular location (Human Protein Atlas): Actin filaments; Nucleoli fibrillar center; Vesicles
Pathways (Reactome):
Signal Transduction: RHO GTPases Activate Rhotekin and Rhophilins
Gene Ontology:
Molecular function: protein binding; beta-catenin binding
Biological process: negative regulation of protein localization to cell surface; regulation of Cdc42 protein signal transduction; Rho protein signal transduction; negative regulation of Wnt signaling pathway; regulation of signal transduction
Cellular component: extracellular exosome; fibrillar center; cytoplasm; cytosol; nucleus; plasma membrane
Genetic constraint (gnomAD): Loss-of-function variants: 13 observed, 14.4 expected, observed/expected ratio (o/e) 0.9, 90% interval 0.59 to 1.43. The upper end of that interval is the gene's LOEUF score, 1.43, which puts it in group 5 of 6, group 1 being the genes least tolerant of losing a copy. Missense variants: 147 observed, 169.81 expected, observed/expected ratio (o/e) 0.87, 90% interval 0.76 to 0.99. Synonymous variants: 70 observed, 62.31 expected, observed/expected ratio (o/e) 1.12, 90% interval 0.93 to 1.37.
Homologues: Orthologues: chimpanzee TAX1BP3 (100% identical), dog TAX1BP3 (100% identical), guinea pig TAX1BP3 (100% identical), macaque TAX1BP3 (100% identical), pig TAX1BP3 (100% identical), rabbit TAX1BP3 (100% identical), mouse Tax1bp3 (99% identical), rat Tax1bp3 (90% identical), tropical clawed frog tax1bp3 (90% identical), zebrafish tax1bp3 (83% identical), Caenorhabditis elegans txbp-3 (41% identical), Drosophila melanogaster CG3402 (40% identical).
Diseases named in the same sentence as TAX1BP3 in open-access papers:
TAX1BP3 is named in the same sentence as 45 diseases in open-access papers, as found by Europe PMC text mining. Sharing a sentence is not in itself a finding about the gene and the disease. The quoted sentences say what the papers report.
glioblastoma (5 papers, 2012 to 2024). The most malignant astrocytic tumor (WHO grade IV). "TAX1BP3 expression could facilitate angiogenesis and tumor formation of human glioblastoma cells and were closely correlated with the prognosis of glioblastoma patients, suggesting that TAX1BP3 can be regarded as a prognostic marker for human glioblastoma." (PMID 37740172, 2023).
invasive breast carcinoma (3 papers, 2021 to 2024). A carcinoma that infiltrates the breast parenchyma. "TAX1BP3 expression levels are increased in human invasive breast cancer, and contribute to cell adhesion to extracellular matrix, invasion and lung metastasis." (PMID 37740172, 2023).
colorectal cancer (2 papers, 2009 to 2023). A primary or metastatic malignant neoplasm that affects the colon or rectum. "Tax1bp3 was initially identified as a player in the proliferation and growth of colorectal cancer cells." (PMID 36892460, 2023).
gastric cancer (1 paper, 2023). A primary or metastatic malignant neoplasm involving the stomach. "Additionally, TAX1BP3 can be a therapy target to regulate chemosensitivity of gastric cancer cells to 5-FU." (PMID 37740172, 2023).
tumor (9 papers, 2010 to 2024). "Recently, it has been reported that Tax1bp3 can be used as an appropriate target for tumour immunotherapy and imaging of cancers, and the monoclonal antibody against Tax1bp3 can be used as a radio‐immunoconjugate moiety to specifically image and treat tumours." (PMID 36892460, 2023).
cancer (6 papers, 2010 to 2023). A tumor composed of atypical neoplastic, often pleomorphic cells that invade other tissues. "Besides, the high expression of Tax1bp3 was associated with adhesion, migration and metastasis of cancer cells, suggesting its function in tumorigenesis." (PMID 36892460, 2023). "Tax1 binding protein 3 (Tax1bp3) is a PDZ domain‐containing protein that is overexpressed in cancer." (PMID 36892460, 2023). "Efforts have been made to clarify the regulatory role of Tax1bp3 in tumorigenesis and metastasis of cancers." (PMID 36892460, 2023). "We previously identified a radiation-inducible neoantigen, Tax interacting protein 1 (TIP-1, also known as Tax1 binding protein 3, (Tax1BP3), that translocates to the cancer cell surface following irradiation." (PMID 27270318, 2016).
TAX1BP3 also shares sentences with these, for which no sentence is quoted: autoimmune disease (2 papers); Autoimmunity (2); diabetes (2); lung carcinoma (2); lupus (2); acute kidney injury (1); Arthritis (1); brain tumors (1); breast carcinoma (1); chronic inflammatory demyelinating polyneuropathy (1); colon cancer (1); depression (1); dilated cardiomyopathy (1); dysplasia (1); glioma (1); Guillain-Barre syndrome (1); Huntington disease (1); Immunodeficiency (1); infection (1); inflammatory bowel disease (1); kidney (1); kidney damage (1); kidney failure (1); Lewis lung carcinoma (1); liver failure (1); Lymphadenopathy (1); malignant glioma (1); melanoma (1); Multiple Organ Failure (1); multiple sclerosis (1).
A further 9 diseases each share a sentence with TAX1BP3 in 1 paper.